INS (insulin)
Diseases named in the same sentence as INS in open-access papers (continued):
Sharing a sentence is not in itself a finding about the gene and the disease.
dementia (continued). "Director indirect effects of insulin could contribute to the risk of dementia." (PMID 37511061, 2023). "However, certain classes with statistical significance tend to have a higher risk for hypoglycaemia, particularly SFU and insulin, which may be inappropriate to be prescribed for the elderly with dementia." (PMID 37476614, 2023). "In addition, higher glucose levels may be a risk factor for dementia, and dietary fiber delays the absorption of carbohydrates and adequately secretes insulin, which leads to reduced post-prandial blood glucose levels." (PMID 35351024, 2022). "In addition, changes in insulin action at the level of the hippocampus affect molecular mechanisms involved in synaptic formation and plasticity, having a negative impact in the maintenance of mental abilities and being a great risk factor for dementia." (PMID 35406040, 2022). "Thus, the aim of the current study is to test whether use of insulin, sulfonylureas and metformin are associated with cognitive performance, cognitive decline, MRI measures and risk of dementia and AD, above and beyond their glycemic control properties." (PMID 30768625, 2019). "However, the insulin or sulfonylureas might increase the risk of severe hypoglycaemia, which was associated with an increased risk of cognitive dysfunction or dementia." (PMID 31296192, 2019). "The association was independent of fasting glucose, BMI, education, and lifestyle factors and was strengthened when follow-up was restricted to ≥20 years, refuting the hypothesis that low insulin was a consequence of weight loss often seen in the prodromal phase of dementia." (PMID 29997193, 2018). "Finally, we note that the APOE genotype was known only in participants who survived until 2000, which may have biased the associations between fasting insulin, genotype, and dementia." (PMID 29997193, 2018). "Thus, chronically high insulin levels have been identified as risk factor for dementia." (PMID 22654904, 2012). "High-frequency keywords included IGF-1, AD, brain, insulin, controlled study, metabolism, oxidative stress, animals, signal transduction, amyloid beta protein, dementia, aging, and neuroprotection." (PMID 41868495, 2026). "Among natural products with diverse mechanisms, components contained in Astragali radix have shown anti-dementia effects in various preclinical studies, including improved cognitive function, reduced β-amyloid levels, and decreased insulin resistance." (PMID 41154559, 2025). "Further assessment also revealed that the metformin + pioglitazone combination showed lower dementia risk than metformin + rosiglitazone, and other combinations (with SU, DPP-4i, insulin, meglitinide, or acarbose) were also beneficial." (PMID 41146261, 2025). "This approach involves the administration of neurotoxic agents to replicate key neuropathological features of dementia, such as oxidative stress, cholinergic dysfunction, insulin resistance, and amyloid plaque formation." (PMID 40725274, 2025). "Important and shared pathological features of T2DM with cognitive decline and dementia, which are characterised by metabolic brain alterations, for example, insulin resistance, altered glucose uptake, and altered glucose utilization." (PMID 40481813, 2025). "About 80% of AD patients are insulin resistant or have T2DM de la Monte, 2014; additionally, T2DM patients have a higher risk of up to 73% dementia than healthy controls do." (PMID 40762561, 2025). "Numerous studies demonstrate that individuals with obesity and/or abnormal insulin metabolism are more prone to the development of cognitive impairments and dementia." (PMID 40806031, 2025). "Common mechanisms believed to accelerate cognitive changes that lead to dementia involve a complex interplay between insulin resistance, oxidative damage, inflammation, cardiometabolic, and lifestyle factors, among others." (PMID 40535512, 2025).
dementia (continued). "In a rat dementia model, islets transplanted into the subarachnoid space restored insulin-dependent brain functions, confirming both viability and endocrine activity." (PMID 41253816, 2025). "Because intranasal insulin has shown promise as a therapeutic agent across a range of individuals from preclinical AD to AD dementia, interest in its further development has been strong." (PMID 40980544, 2025). "This suggests the potential role of IGF-1 as a novel therapeutic target, also in combination with insulin, in the treatment of dementia in sporadic Alzheimer’s disease." (PMID 40283962, 2025). "Reaching a better understanding of how the brain responds to insulin is likely to improve our capacity to possibly treat and prevent dementia, and possibly AD as well." (PMID 37611907, 2024). "The participants were split into three groups receiving placebo (n = 30), 20 IU intranasal insulin (n = 36), or 40 IU intranasal insulin (n = 38) with the primary measures set as delayed story recall and Dementia Severity Rating Scale score." (PMID 38255204, 2024). "In fact, DM shares similar pathophysiological mechanisms with dementia, such as systemic inflammation, oxidative stress, insulin resistance and advanced glycation end-products formation." (PMID 39200215, 2024). "A network meta-analysis including nineteen eligible studies (n = 4855) was conducted to evaluate the effects of 6 different antidiabetic drugs (intranasal insulin, pioglitazone, rosiglitazone, metformin, sitagliptin and liraglutide) on dementia." (PMID 38881878, 2024). "Pathomechanisms of dementias involve increasing damage to neuronal energy metabolism, resulting in degeneration-related insulin resistance and glucose hypometabolism." (PMID 38715705, 2024). "Since insulin signaling is essential in learning and memory, increasing insulin sensitivity can effectively combat dementia." (PMID 38333746, 2024). "Our data suggested that IP or ICV-STZ administration in rats results in a significant time dependent deterioration of learning and memory and indicated that impaired insulin signaling contributes to the development and progression of dementia as in sAD." (PMID 38260013, 2023). "It is theorized that dementia from T2DM stems from the fact that the brain is susceptible to hyperglycemic conditions, which are promoted by the increase in insulin resistance of target cells in the central nervous system." (PMID 38152822, 2023). "Insulin injection was long anticipated to be a successful dementia treatment since insulin imbalances in the central nervous system have been linked to the onset of neurodegeneration." (PMID 37113972, 2023). "This was motivated by observations of a U-shaped relationship between fasting insulin in middle age and dementia up to 34 years later." (PMID 37420130, 2023). "DM and dementia share some common features, such as severe and chronic neuroinflammation, brain-insulin resistance, an overaccumulation of Aβ and a disrupted BBB integrity." (PMID 37373216, 2023). "Clinical trials evaluating insulin sensitizers as potential DMTs for dementia have yielded varying results based on the drug classes studied." (PMID 37511207, 2023). "The emerging understanding of the brain’s insulin sensitivity has shed light on the potential link between insulin-related conditions and dementia." (PMID 37511207, 2023). "The early onset of these alterations and the finding that they correlate with rats’ cognitive performance highlights the primary role of impaired insulin signaling in the onset of dementia." (PMID 37443762, 2023). "Further, studies suggest a direct connection between metabolic defects, amyloid deposition, and dementia, as insulin levels can impact the production and deposition of amyloid-ß in the brain and brain insulin resistance can predict development of AD in DS." (PMID 37323671, 2023).
dementia (continued). "The available scientific evidence on this relationship supports that the first pathological event in the DM disorder, as a promoter of dementia, is insulin resistance in the CNS." (PMID 37873836, 2023). "As compared with placebo-assigned participants, those receiving both doses of insulin had significantly preserved Dementia Severity Rating Scale (DSRS) scores." (PMID 37176592, 2023). "Researchers are currently trying to repurpose anti-diabetic drugs to treat dementia, which are dominated by insulin sensitizers and insulin substrates." (PMID 37511207, 2023). "We also describe the molecular perspectives of various types of dementia through the insulin/IGF-1 signaling pathway." (PMID 37511207, 2023). "Patients with T2DM under treatment with DPP4is presented with the lowest risk of dementia, followed by those treated with metformin and TZD, while treatment with insulin was associated with the highest risk." (PMID 36909158, 2023). "First, with intranasal insulin to augment the body’s natural counter-reaction to the changes in brain cell-types that produced the dementia." (PMID 37176592, 2023). "In contrast, people with established dementia show insulin disturbances, with altered fasting glucose levels." (PMID 37873836, 2023). "Given that impaired insulin signaling in the brain is one of the characteristics of AD patients, strategies for repurposing anti-diabetic drugs as a therapeutic option for dementia have been proposed." (PMID 37511207, 2023). "Hormone signaling, particularly in the glucose/insulin pathway, is disrupted in APOEε4 individuals and can increase the severity of dementia." (PMID 35370604, 2022). "In this article, we will discuss the role of insulin signaling in the development of dementia and other neurological disorders." (PMID 36497027, 2022). "A growing body of epidemiological and molecular evidence now suggests an obvious relationship between brain insulin resistance, dementia due to Alzheimer's disease (AD), Parkinson's disease (PD), and AD/PD-related dementias." (PMID 36060240, 2022). "The development of novel treatment options for T2DM in dementia IR is developed due to altered insulin signaling, which is essential for energy metabolism, neuronal growth, neuroprotection, and synaptic plasticity." (PMID 36497027, 2022). "Some small, single-site studies indicated that intranasal insulin can enhance memory in patients with MCI or dementia." (PMID 36172480, 2022). "Since insulin abnormalities in the central nerve system have been associated with the development of neurodegeneration, for many years insulin administration was expected to be an effective dementia treatment." (PMID 35742986, 2022). "The serine-threonine protein kinase B (AKT1/2) and GSK3-β are involved in the brain insulin/insulin-like growth-factor-1 (IGF-1) signaling whose dysregulation correlates with the severity of dementia symptoms in sAD." (PMID 34830036, 2021). "Telmisartan is the only ARB that, at a clinical dose, has agonistic effects on peroxisome proliferator-activated receptor γ (PPAR-γ), which maintains insulin sensitivity, reduces insulin resistance, and potentially has a protective impact on dementia." (PMID 34280191, 2021). "Early dementia signs (insulin sensitivity, cognitive dysfunction, neuronal injury) were evident in Stressed compared to non-Stressed individuals." (PMID 33670473, 2021). "Glucose deregulation and decreased action of insulin are central to the development and progression of dementia in diabetic patients." (PMID 34837961, 2021). "Insulin has been considered of particular importance for dementia and early changes of glucose metabolism." (PMID 32265637, 2020). "The inverse relationship in dispensation rates suggests a link between the increase in insulin and decrease in metformin and sulfonylurea, independently of dementia or renal status." (PMID 32741836, 2020).
dementia (continued). "The estimates from the linear regression in the matched cohort showed steeper yearly increase in insulin prescription in dementia patients compared to dementia-free controls (1.96% versus 0.99%)." (PMID 32741836, 2020). "Dementia patients had lower probability of receiving newer antidiabetic drugs, with simultaneous higher insulin dispensation compared to dementia-free subjects." (PMID 32741836, 2020). "Dementia patients had higher probability of insulin dispensation (hazard ratio 1.21 [95% CI 1.11–1.31] and lower probability of DPP-4i (0.72 [0.66–0.79]), GLP-1a (0.51 [0.41–0.63]), and SGLT-2i dispensation (0.44 [0.36–0.54]) after index date." (PMID 32741836, 2020). "The whole cohort experienced frequent insulin dispensation; however, patients with dementia had significantly higher rate of insulin usage and this was apparent even in the yearly-stratified analyses." (PMID 32741836, 2020). "With the current emerging knowledge on the regulation and function of brain insulin signaling, there is a need for further research into how insulin/glucose metabolism intersects with dementia in APOE isoform-dependent manner." (PMID 32005122, 2020). "The target genes of the differentially expressed miRNAs were involved in pathways related to endothelial cell permeability and function, cell signaling, insulin signaling/resistance, apoptosis, and dementia." (PMID 32545722, 2020). "On the other hand, D-gal increased serum insulin levels and insulin resistance in the brain, which leads to dementia." (PMID 32570962, 2020). "The links between dementia-related symptoms and the abnormal activation of tyrosine kinase pathways, cardiovascular disease, and impaired insulin sensitivity are reflected by the presence of these agents in the pipeline of repurposed drugs." (PMID 32807237, 2020). "Analyses stratified on index year showed relatively consistently higher dispensation of insulin in dementia versus non-dementia subjects." (PMID 32741836, 2020). "In fact, there is strong evidence supporting a pathophysiological link between T2DM, dementia and Alzheimer’s disease, possibly related to glycemic control and insulin dysregulation." (PMID 33120406, 2020). "The impairment of insulin signaling (leading to insulin resistance) in the brain plays an essential role in the pathogenesis of dementia and precedes cognitive dysfunction and pathological alterations even by decades." (PMID 31835729, 2019). "These miRNA target genes are involved in different pathways such as those related to endothelial cell permeability and function, insulin signaling/resistance, and dementia." (PMID 31836762, 2019). "While disrupted glucose regulation is correlated with cerebral hyperexcitability and accumulation of pathology, disrupted insulin signaling and insulin resistance also have strong associations with MCI, dementia, and AD." (PMID 31616284, 2019). "Here we review encouraging preclinical and clinical data indicating the potential of targeting impaired insulin signaling with antidiabetic drugs to treat dementia." (PMID 30542257, 2018). "Regarding dementia endpoints, reduced risk was seen for low and medium tertiles of HOMA insulin sensitivity compared to the high tertile." (PMID 29997193, 2018). "Metabolic disease is a risk factor for developing dementia, and symptom progression in dementia has been slowed with drugs potentiating insulin signaling in rodents and in humans." (PMID 29790000, 2018). "Since insulin has a central role in learning and memory, and adiponectin an insulin-sensitizing effect, the latter represents a potential therapeutic target against dementia." (PMID 30002734, 2018). "This suggests that the coadministration of insulin with L-penetratin is a useful way to facilitate nose-to-brain delivery of insulin and further to prevent and cure dementia in the early stage." (PMID 30518944, 2018).
dementia (continued). "Insulin and insulin receptors show abundant expression throughout the brain, especially in the hippocampus, which is involved in dementia." (PMID 29850612, 2018). "Most of the rodent models used to investigate the role of insulin and glucose metabolism in dementia have focused on AD." (PMID 30072954, 2018). "To overcome the difficulty of therapy via nose-to-brain delivery of insulin in the progressive stage of dementia, we focused on the potential of GLP-1 and its analogs as alternative drug candidates." (PMID 30518944, 2018). "Recently, emerging data suggest that impaired insulin signaling is the major contributor in the development of Alzheimer’s dementia (AD), which is the most common type of senile dementia." (PMID 28832656, 2017). "As the population ages, neurodegenerative disorders become epidemic and a connection between insulin signaling dysregulation, cognitive decline and dementia has been established." (PMID 27713238, 2009). "It has also been shown to enhance attention and everyday functioning in older adults along a spectrum from cognitive health to dementia, and some studies suggest that intranasal insulin may modulate plasma beta amyloid and other AD biomarkers." (PMID 40980544, 2025). "It has been reported that both oral hypoglycemic drugs and insulin do not significantly interfere with the risk to develop dementia when included as covariables in a longitudinal observational study." (PMID 41146261, 2025). "Offering adjunct therapies to GLP-1RA use in advanced stages of dementia, such as cholinesterase inhibitors and monoclonal antibodies, raises the possibility of synergistic effects, such as neuroinflammation and insulin signalling modulation potentiating the effects of amyloid clearance." (PMID 40210453, 2025). "Otherwise, the relation of insulin and worse cognitive performance may highlight the significance of metabolic pathways in the development of dementia." (PMID 40818936, 2025). "In parallel, it has also been reported that metformin cessation might increase the incidence of dementia, independently of changes in HbA1 levels or use of insulin in a large study including race as covariable." (PMID 41146261, 2025). "Five SRs were included, analyzing the effects of simvastatin, antioxidants, acetyl-L-carnitine, anticonvulsants, acetylcholinesterase inhibitors (donepezil), NMDA receptor antagonists (memantine), and fast-acting intranasal insulin on dementia symptoms in DS patients." (PMID 40860508, 2025). "This hypothesis was tested by examining postmortem cases of advanced AD and detecting abnormal expressions of genes encoding insulin, as well as IGF peptides and their receptors, that correlated with the development and progression of lesions and dementia." (PMID 39857716, 2025). "The link between insulin levels, oxidative stress, and dementia requires further research." (PMID 38542318, 2024). "There is increasing evidence suggesting that the activation of AMPK may have extensive neuroprotective effects for dementia, such as promoting autophagy, maintaining mitochondrial quality control, reducing insulin resistance, and alleviating oxidative stress." (PMID 38881878, 2024). "In this paper, we highlight the possibility of repositioning anti-diabetic drugs as a strategy for dementia therapy by analyzing clinical trials as well as integrating the molecular perspectives from various types of dementia through the insulin/IGF-1 signaling pathway." (PMID 37511207, 2023). "Pioglitazone, an insulin sensitizer, should have a role in treating dementia." (PMID 37036483, 2023). "There’s also increased mortality in insulin users who develop dementia." (PMID 38152822, 2023). "Meanwhile, the clinical trial regarding insulin treatment in other forms of dementia is limited." (PMID 37511207, 2023). "They further assessed whether the use of penetratin as a delivery agent could increase the pharmacological efficacy of insulin in the treatment of dementia." (PMID 37371113, 2023).